ALK (ALK receptor tyrosine kinase)
Diseases named in the same sentence as ALK in open-access papers (continued):
Sharing a sentence is not in itself a finding about the gene and the disease.
neuroblastoma (continued). "We have also shown that a single color ALK CISH assay enables detection of ALK genomic amplification in neuroblastomas." (PMID 25188507, 2014). "Both CEP-26939 and its closely related analog ALK inhibitor, CEP-28122, have been reported to lead to growth inhibition in a variety of cultivated human ALK-related cancer cell lines, including neuroblastoma, through caspase 3/7 activation and apoptosis." (PMID 23667670, 2013). "Given recent observations that ALK regulates MYCN transcription in neuroblastoma cells and collaborates with MYCN in neuroblastoma pathogenesis 34–37, we decided to investigate a role for STAT3 in this process." (PMID 23889739, 2013). "TAE-684 is a small molecule inhibitor of activated anaplastic lymphoma kinase (ALK) and reduces cell viability of ALK mutated neuroblastoma cells." (PMID 23977142, 2013). "As such, several therapeutic options have been developed for ALK-positive neuroblastoma, and the small molecule inhibitor Crizotinib has displayed encouraging results in early phase pediatric trials." (PMID 24349301, 2013). "Anaplastic Lymphoma Kinase (ALK) was initially discovered as an oncogene in human lymphoma and other cancers, including neuroblastoma." (PMID 23667670, 2013). "Increased copy numbers and gene amplifications of the ALK locus is also often detected in neuroblastoma patients." (PMID 23667670, 2013). "We show here that activated ALK robustly activates STAT3 on Tyr705 in a number of independent neuroblastoma cell lines." (PMID 23889739, 2013). "We first investigated the impact of ALK mutation on receptor phosphorylation by comparing two neuroblastoma cell lines, IMR-32 cells expressing only wild-type receptor and SH-SY5Y cells exhibiting a heterozygous ALK F1174L activating mutation." (PMID 22479414, 2012). "An interesting connection between ligand-dependent ALK signaling, sympathetic neurogenesis, and neuroblastoma was provided recently in a study on the timing of sympathetic neurogenesis." (PMID 23267434, 2012). "As stated by Fischer and colleagues the 11q-deletion is most likely a secondary event, and it is possible that the decision between favourable and unfavourable neuroblastoma is made by a yet undefined transformation event, for example ALK." (PMID 21492432, 2011). "Crizotinib also inhibits the proliferation in NSCLC (such as H3122) and neuroblastoma cell lines harboring ALK activation." (PMID 21504625, 2011). "These subcategories included many genes known to be important in neuroblastoma pathogenesis, including ALK, AURKA and BDNF." (PMID 21731748, 2011). "Although ALK is commonly expressed in the cytoplasm of neuroblastoma cells, its amplification has so far been demonstrated in only 1 of 85 tumor samples." (PMID 17327916, 2007). "Suppression of activated ALK in neuroblastoma cells by RNA interference was shown to lead to rapid apoptosis." (PMID 16989664, 2006). "ALK (anaplastic lymphoma kinase) receptor, an oncogene and reported highly expressed in neuroblastoma, was identified to be amplified in two of our tumor samples." (PMID 15380028, 2004). "A 4-year-old male patient with high-risk neuroblastoma (stage 4, N-Myc non-amplified, anaplastic lymphoma kinase [ALK] negative) was initially treated with induction chemotherapy, surgical resection, and adjuvant abdominal proton therapy." (PMID 41362481, 2026). "Advances in molecular biology and genomics have significantly improved understanding of neuroblastoma pathogenesis, revealing the critical role of genetic and epigenetic alterations-such as MYCN amplification, ALK mutations, and chromosomal aberrations-in disease behavior and prognosis." (PMID 41682783, 2026). "To characterize ALK surface binding and internalization kinetics in neuroblastoma cell lines with varying levels of ALK expression, we conjugated CDX0239 to Fabfluor-pH Orange labeling dye designed for labeling Fc-containing antibodies with a pH sensitive fluorophore." (PMID 40813394, 2025).
neuroblastoma (continued). "The in vivo experiments were conducted using a murine neuroblastoma model (Neuro-2a, ALK+)." (PMID 40574837, 2025). "The first phase I study of the New Approaches to Neuroblastoma Therapy Consortium (NANT2015-02) in children (NCT03107988) explored the use of loratinib in patients with ALK-driven refractory or relapsed neuroblastoma, demonstrating the drug’s safety profile and significant clinical activity." (PMID 40115016, 2025). "A phase I/II study of crizotinib in combination with another mTOR inhibitor, temsirolimus, in relapsed or refractory neuroblastoma with ALK or MET aberrations is currently ongoing, although unexpected toxicity caused by temsirolimus was detected (EUCTR2015-005437-53)." (PMID 41511287, 2025). "Indeed, strategies to upregulate surface ALK using ALK inhibitors in neuroblastoma or to upregulate surface CD72 using SHIP1 inhibitors in B-ALL significantly improves CAR T-mediated killing." (PMID 40931013, 2025). "Mutant ALK has been therapeutically targeted in neuroblastoma with small molecular enzymatic inhibitors that have been implemented from the original discoveries of germline and somatic ALK mutations, to preclinical proof-of-concept, through early and late-phase clinical implementation (NCT03126916)." (PMID 40813394, 2025). "Finally, we show that CDX0239-PBD exhibits potent antitumor efficacy including maintained complete responses in ALK-expressing patient and cell line-derived neuroblastoma, fusion-positive rhabdomyosarcoma, and colorectal carcinoma xenograft models." (PMID 40813394, 2025). "Whole exome sequencing results revealed that such EV-DNA carried tumor-specific genetic mutations, including those occurring on known oncogenes and tumor suppressor genes in neuroblastoma (ALK, CHD5, SHANK2, PHOX2B, TERT, FGFR1, and BRAF), and represented the entire exome." (PMID 39402599, 2024). "We conclude that ctDNA analysis may guide treatment decisions in ALK-driven neuroblastoma, also when the disease is undetectable using standard clinical methods." (PMID 39177282, 2024). "This could be a promising strategy as ALK activation is known to drive neuroblastoma growth, and therapies targeting ALK have shown efficacy but are prone to resistance and adverse effects." (PMID 38397899, 2024). "Additionally, the study unveiled complex mechanisms of ALK degradation, contingent upon its cellular location, offering insights into potential strategies to inhibit neuroblastoma proliferation by targeting these degradation pathways." (PMID 38397899, 2024). "Gain-of-function in ALK could drive the neuroblastoma but requires cooperation from MYCN amplification." (PMID 38391759, 2024). "This has led to extensive studies on the combination of various small-molecule drugs, including epidermal growth factor receptor inhibitors in esophageal squamous cell carcinoma, BRAF or MEK inhibitors in melanoma, ALK inhibitors in neuroblastoma, and immune checkpoint inhibitors." (PMID 39000513, 2024). "In addition, signaling through the IGF1R/PI3 kinase/AKT/mTOR pathway facilitates neuroblastoma metastasis to bone and induces resistance to cytotoxic chemotherapy, retinoic acid, and ALK inhibitors." (PMID 39001383, 2024). "Here, the authors identify loss of miR-1304-5p as a driver of ALK inhibitor resistance via regulation of NRAS, and therapeutically target this axis with the addition of a farnesyltransferase inhibitor in preclinical models of neuroblastoma." (PMID 38653965, 2024). "Activating mutations in the receptor tyrosine kinase ALK and loss of function mutations or deletions of genes important for chromatin remodeling, including ATRX, ARID1A, and ARID1B, are observed in high-risk neuroblastoma." (PMID 39001383, 2024).
neuroblastoma (continued). "ALK.CAR‐Ts were as effective as GD2.CAR‐Ts against a large panel of neuroblastoma lines." (PMID 38877641, 2024). "Targeting Anaplastic lymphoma kinase (ALK) is a promising therapeutic strategy for aberrant ALK-expressing malignancies including neuroblastoma, but resistance to ALK tyrosine kinase inhibitors (ALK TKI) is a distinct possibility necessitating drug combination therapeutic approaches." (PMID 38653965, 2024). "Also, antibody–drug conjugate directed to ALK demonstrated some efficacy against neuroblastoma in preclinical models." (PMID 38877641, 2024). "False‐positive ALK expression also occurs in other types of tumors, such as neuroblastoma, which may be mediated by MYCN amplification." (PMID 39667359, 2024). "We conclude that some patients with relapsed or refractory high-risk neuroblastoma show durable responses to lorlatinib as monotherapy, and targeted ctDNA analysis is effective for evaluation of treatment and early detection of relapse in ALK-driven neuroblastoma." (PMID 39177282, 2024). "Patients with anaplastic lymphoma kinase (ALK)–driven neuroblastoma may respond to tyrosine kinase inhibitors, but resistance to treatment occurs and methods currently used for detection of residual disease have limited sensitivity." (PMID 39177282, 2024). "Here, we present a national unselected cohort of five patients with relapsed or refractory ALK-driven neuroblastoma treated with lorlatinib as monotherapy and test the potential of targeted circulating tumor DNA (ctDNA) analysis as a guide for treatment decisions in these patients." (PMID 39177282, 2024). "Interestingly, this inhibition only affected cell proliferation and survival in ALK+ neuroblastoma cells, suggesting a potential therapeutic strategy." (PMID 38397899, 2024). "Conversely, obstructing matrix metallopeptidase 9 (MMP-9) could impede ALK cleavage, reducing migration and invasion of neuroblastoma cells, hinting at a promising therapeutic approach." (PMID 38397899, 2024). "Together, these results raise the hypothesis that older patients with ALK-driven neuroblastoma may respond to lorlatinib as monotherapy, whereas young children harboring an MYCN amplification may benefit more from a combination regimen." (PMID 39177282, 2024). "Although the presence of ALK is associated with a worse prognosis in neuroblastoma and rhabdomyosarcoma, the same does not apply to medulloblastomas." (PMID 38339401, 2024). "Moroever, repotrectinib showed antitumor efficacy in ALK-dependent neuroblastoma cells." (PMID 37954850, 2023). "Thereafter, aberrant ALK, either as a fusion partner or a full-length protein with activating mutations or overexpression, has been reported in a wide range of human malignancies including non-small cell lung cancer (NSCLC) and neuroblastoma (NB)." (PMID 38264745, 2023). "Finally, we show that lorlatinib-resistant ALK-F1174L neuroblastoma cells harbor additional RAS-MAPK pathway alterations and can be resensitized to lorlatinib when combined with TNO155 in vitro and in vivo." (PMID 38032104, 2023). "The most frequently harbored alterations of specific genes in neuroblastoma include heritable mutations in the ALK and PHOX2B observed in familial neuroblastoma, chromatin remodeling genes like ATRX, ARID1A and ARID1B and other important genes like PTPN11, MYCN, and NRAS." (PMID 37274289, 2023). "Taken together, this suggests that SHP2 inhibitors, like ALK-TKIs, are more effective in the context of ALK hyperactivation and that this selectivity could be exploited in ALK-mutant neuroblastoma." (PMID 38032104, 2023). "ALK VAF was found to correlate with clinical course in some patients with neuroblastoma." (PMID 37954850, 2023). "Regardless, in neuroblastoma cell lines in which ALK is either amplified (SK-N-AS: ALK is transcriptionally controlled by MYCN) or mutated (LAN-5: ALKR1275Q), MYCN was reported to disrupt the normal cellular circadian rhythm to promote a lipogenic transcriptional program." (PMID 37414143, 2023).
neuroblastoma (continued). "Although lorlatinib treatment has reportedly been more successful at delaying ALK inhibitor resistance compared with other ALK-TKIs, certain cancer models including relapsed ALK-F1174L neuroblastomas have been shown to eventually acquire resistance after long-term treatment." (PMID 38032104, 2023). "Moreover, treatment with TNO155 and ALK-TKIs synergistically reduced cell growth and promoted inactivation of ALK and MAPK signaling in ALK-mutant neuroblastoma cells." (PMID 38032104, 2023). "Here we present the safety, tolerability and anti-tumor activity of a first-in-child New Approaches to Neuroblastoma Therapy (NANT) Consortium phase 1 study (NANT2015-02) of lorlatinib in children, adolescents and adults with ALK-driven refractory or relapsed neuroblastoma." (PMID 37012551, 2023). "Crizotinib, a first-generation ALK inhibitor approved for ALK-translocated lung tumors, was less effective in preclinical neuroblastoma models, especially in tumors harboring the neuroblastoma-associated ALK-F1174L mutation which showed innate resistance to this therapy." (PMID 38032104, 2023). "It is hypothesized that ALK overexpression generates a defect in the differentiation of neural crest cells in neuroblastoma." (PMID 37443767, 2023). "Four neuroblastoma cell lines were included based on the presence of the most common mutations affecting the RAS-MAPK pathway, RAS (KRAS in SJNB8 and NRAS in SKNAS), NF1 (SKNBE) and ALK (KCNR)." (PMID 36895472, 2023). "Additionally, mutations in the paired-like homeobox 2B (PHOX2B) and anaplastic lymphoma kinase (ALK) genes have been detected in patients with rare familial neuroblastoma." (PMID 37835497, 2023). "We noted, however, that ALK amplification frequencies at relapse were significantly elevated in patients <18 months with stage 4 disease as compared to patients ≥18 months with stage 4 neuroblastoma (16.7% versus 2.9%, P = 0.041)." (PMID 36807339, 2023). "The ALK interactome analysis (which flagged IRS2 as a major component of ALK signalling in neuroblastoma) discovered a number of glycolytic enzymes (glucose-6-phosphate isomerase, aldolase, triosephosphate isomerase 1, and phosphoglycerate mutase 1) in the ALK-interacting network." (PMID 37414143, 2023). "However, pediatric clinical trials have shown limited long-term single-agent ALK-TKI activity for neuroblastoma, because innate or acquired resistance often leads to drug inefficacy and tumor recurrence." (PMID 38032104, 2023). "Furthermore, mutations in the intracellular kinase domain and gene copy amplifications resulting in aberrant ALK activity have also been reported, specifically in neuroblastoma (NBL) and NSCLC, respectively." (PMID 37765282, 2023). "The discovery of the receptor tyrosine kinase ALK as a target of genetic alterations in cases of familial and sporadic neuroblastoma, was a breakthrough in the understanding of the complex genetic heterogeneity of neuroblastoma." (PMID 37414143, 2023). "Notably, adolescents and adults with ALK-driven neuroblastoma had objective and sustained responses, an important outcome for patients who often have an indolent clinical course with de novo chemotherapy resistance and an abysmal overall outcome." (PMID 37012551, 2023). "The discovery of Augs has led scientists to expand the patient subpopulation that could be targeted with ALK inhibitors, as Augα overexpression in mice almost completely reproduces ALK-MYC synergy in driving neuroblastoma." (PMID 37892172, 2023). "The ALK protein is a receptor tyrosine kinase that is frequently activated in pediatric malignancies, such as anaplastic large cell lymphoma, inflammatory myofibroblastic tumor, rhabdomyosarcoma, and neuroblastoma." (PMID 36807339, 2023).